LRRC70 (leucine rich repeat containing 70)
Description:
Renders cells highly sensitive to the activation by cytokines and lipopolysaccharide (LPS).
Synonyms: SLRN; LOC100130733
Tractability: Antibody: its Gene Ontology location is reachable by antibodies, with high confidence; UniProt predicts a signal peptide or a membrane-spanning region.
Gene: Protein-coding gene on chromosome 5 (62,578,819 to 62,581,446, forward strand). Ensembl gene ENSG00000186105.
Subcellular location: Membrane
Gene Ontology:
Biological process: positive regulation of response to cytokine stimulus
Cellular component: plasma membrane; membrane
Genetic constraint (gnomAD): Loss-of-function variants: 29 observed, 42.18 expected, observed/expected ratio (o/e) 0.69, 90% interval 0.51 to 0.94. The upper end of that interval is the gene's LOEUF score, 0.94, which puts it in group 3 of 6, group 1 being the genes least tolerant of losing a copy. Missense variants: 616 observed, 712.36 expected, observed/expected ratio (o/e) 0.86, 90% interval 0.81 to 0.92. Synonymous variants: 261 observed, 267.03 expected, observed/expected ratio (o/e) 0.98, 90% interval 0.88 to 1.08.
Homologues: Orthologues: dog LRRC70 (89% identical), pig LRRC70 (88% identical), tropical clawed frog lrrc70 (42% identical), chimpanzee LRRC70 (11% identical). Paralogues in human: LRRN1 (22% identical), LRRN2 (22% identical), SLIT3 (22% identical), LRRN3 (22% identical), SLIT2 (21% identical), SLIT1 (21% identical), SLITRK3 (20% identical), TLR9 (19% identical), SLITRK5 (19% identical), SLITRK2 (18% identical), SLITRK4 (18% identical), SLITRK6 (18% identical), and 13 more.